PAK2 (p21 (RAC1) activated kinase 2)
Diseases named in the same sentence as PAK2 in open-access papers (continued):
Sharing a sentence is not in itself a finding about the gene and the disease.
schwannoma (3 papers, 2018 to 2024). A benign, usually encapsulated slow growing tumor composed of Schwann cells. "Due to the cardiotoxicities associated with PAK2 inhibition, recent developments in PAK1-specific drugs have been of interest for Merlin-deficient schwannomas." (PMID 39083549, 2024). "In addition, one investigation highlighted the pivotal role of PAK2 in the activation of Wnt/β-catenin signaling in Schwannoma cells, with depletion of PAK2 resulting in diminished levels of active β-catenin, c-Myc, and cyclin D1." (PMID 39769207, 2024). "PAK2 modulates STAT3 signaling to enhance cyclin D1 expression; activates Wnt/β-catenin signaling in Schwannoma cells." (PMID 39769207, 2024).
viral infection (3 papers, 2011 to 2025). "We observed that PAK2 activation is a critical priming step for TFEB degradation as this kinase is activated by viral infection, generating a phospho-degron required for subsequent DCAF7 recognition (see the model in fig." (PMID 40465712, 2025). "In particular, viral infection triggers marked PAK2 activation, which in turn, phosphorylates and primes TFEB for ubiquitin-mediated protein degradation." (PMID 34013250, 2021). "Furthermore, PAK2 KO notably mitigated the virally induced decline in TFEB protein, and endogenous TFEB ubiquitination was substantially decreased in PAK2 KO cells during viral infection." (PMID 40465712, 2025).
acute myocardial infarction (2 papers, 2022 to 2023). Necrosis of the myocardium, as a result of interruption of the blood supply to the area. "Another bioinformatically predicted and validated pathway is the lncRNA FAF/miR-185-5p/PAK2 axis that mediates cardiomyocyte pyroptosis to ameliorate acute myocardial infarction." (PMID 37396588, 2023). "It is reasonable to believe that lncRNA FAF promotes the release of PAK2 by inhibiting the miR-185-5p pyroptosis pathway, which attenuates the cellular pyroptosis response and reduces the size of myocardial infarction." (PMID 37396588, 2023).
atherosclerosis (2 papers, 2024 to 2025). A disease characterized by the build-up of fatty material and calcium deposition in the arterial wall resulting in partial or complete occlusion of the arterial lumen. "The dysregulation of PAK2 has also been implicated in inflammatory diseases, such as atherosclerosis, rheumatoid arthritis, and diabetic vasculopathy, in which altered PAK2 activity may lead to chronic inflammation in perivessels." (PMID 39766303, 2024). "NETs impair wound healing under diabetic conditions by suppressing the toll-like receptor 9 (TLR9)-p21-activated kinase 2 (PAK2)-dependent Hippo-YAP signaling pathway and development of atherosclerosis by inducing TLR9/NF-κB-mediated interleukin-8 (IL-8) secretion in macrophages." (PMID 41008570, 2025).
autism spectrum disorder (2 papers, 2023 to 2024). A spectrum of developmental disorders that includes autism, and Asperger syndrome. "Neurological illnesses linked to PAK2 mutations include autism spectrum disorder, 3q29 microdeletion syndrome, and AD." (PMID 39050707, 2024).
Autoimmunity (2 papers, 2017 to 2022). The occurrence of an immune reaction against the organism's own cells or tissues. "PAK2 is essential in T cell development and differentiation, indicating its potential function in T cell-initiated autoimmunity." (PMID 36741695, 2022).
cervical cancer (2 papers, 2021 to 2023). A primary or metastatic malignant neoplasm involving the cervix. "Consistently, PAK2 has been shown to act as an effector to confer drug resistance and malignant properties in breast and cervical cancer." (PMID 36740679, 2023).
colon adenocarcinoma (2 papers, 2020 to 2021). "Moreover, PAK2 has been reported to be a downstream target gene of miR-455-3p in human osteoblasts and in human colon adenocarcinoma cells." (PMID 33708992, 2021).
colon cancer (2 papers, 2018 to 2023). "In these frozen tissue specimens from colon cancer patients, lower miR-4779 expression was observed in 6 of 10 pairs of tumors compared with normal tissues, whereas PAK2 and CCNCD3 proteins were highly upregulated in tumors." (PMID 29362401, 2018). "Finally, miR-4779 expression was low in 9 of 10 colon cancer tissues, whereas PAK2 and CCND3 expressions were significantly high in colon cancer tissues." (PMID 29362401, 2018).
diabetes (2 papers, 2022 to 2023). "In addition, as functional evidence, we showed that un-mitigated cardiac ER response due to PAK2 loss under diabetes may account as a barrier for leveraging the anti-inflammatory potential of vildagliptin." (PMID 35281739, 2022). "We found that the expression of PAK2 was elevated after diabetes, which suppressed the expression of GLUT4 through PI3K/AKT pathway." (PMID 37610708, 2023). "To investigate the mechanism of diabetes-induced neuronal death, we examined the effects of PAK2 inhibition on neurotoxicity under high-glucose exposure." (PMID 37610708, 2023). "Consistent with the clinical findings, PAK2 activation was also enhanced in the myocardium during the early stages of diabetes, with a significant decline in expression and phosphorylation levels later." (PMID 35281739, 2022). "We dissect that PAK2 is a regulator of ER stress response in diabetes with an increase in CHOP because of the dysregulated ER response." (PMID 35281739, 2022). "Noteworthy, under diabetes, the expression and phosphorylation of PAK2, an ER stress response modulator, were both decreased in the human heart." (PMID 35281739, 2022). "Prompted by the decline in cardiac PAK2 in long-term diabetes, our data provide a hypothetical explanation for clinical outcomes where vildagliptin has a limited effect on cardiac function due to its futile effect on PAK2 activation." (PMID 35281739, 2022). "Considering that cardiac PAK2 was abolished during diabetes development, we postulated that restored PAK2 serves as a molecular basis for supporting vildagliptin-induced ER regulation." (PMID 35281739, 2022). "By contrast, the expression of PAK2 and Sp8 was significantly increased after diabetes induction." (PMID 37610708, 2023). "It suggested that PAK2 pathway may be involved in cognitive dysfunction in diabetes and could be a therapeutic target for Gastrodin intervention." (PMID 37610708, 2023). "Furthermore, as a cardiac ER dysfunction model, mice with cardiac-specific p21-activated kinase 2 (PAK2) deletion exhibited heightened myocardial inflammatory response in diabetes." (PMID 35281739, 2022). "Moreover, p21 activated kinase 2 (PAK2) was found to be important for diabetes-induced hippocampal injury and its inhibitor could promote the survival of primary hippocampal neurons." (PMID 37610708, 2023). "However, whether the role of cardiac PAK2 in modulating ER stress is recapitulated in diabetes is unknown." (PMID 35281739, 2022). "Though many studies have found that Gastrodin treated diabetes through PI3K/AKT pathway, our study was the first to report that the PAK2 is important for the effect of Gastrodin." (PMID 37610708, 2023). "Therapeutically, activated-PAK2 remediated ER function, and extracellular inhibition of HMGB1 represses ER stress-induced inflammation and subsequent dysfunction in diabetes." (PMID 35281739, 2022).
glioma (2 papers, 2022 to 2025). A benign or malignant brain and spinal cord tumor that arises from glial cells (astrocytes, oligodendrocytes, ependymal cells). "The difference of PAK2 protein in glioma samples is similar to that of PAK1." (PMID 36064705, 2022).
ischemia (2 papers, 2022). A hypoperfusion of the BLOOD through an organ or tissue caused by a PATHOLOGIC CONSTRICTION or obstruction of its BLOOD VESSELS, or an absence of BLOOD CIRCULATION. "Activation of 5′ AMP-activated protein kinase (AMPK)-p21-activated kinase 2 (PAK2) signaling attenuated ER stress and myocardial apoptosis induced by ischemia/reperfusion injury." (PMID 35321102, 2022). "Moreover, activation of 5′AMP-activated protein kinase (AMPK)-p21-activated kinase 2 (PAK2) signaling attenuated ER stress and myocardial apoptosis induced by ischemia/reperfusion injury." (PMID 35784716, 2022).
Knobloch syndrome (2 papers, 2025). "Recently, a novel variant in PAK2 was identified in a newborn exhibiting features consistent with Knobloch syndrome, specifically atretic parietal meningocele and presumed retinopathy of prematurity (ROP)." (PMID 41153400, 2025). "Due to the ocular anomalies and meningocele, this study concluded that the kinase-deficient PAK2 variant contributes to the pathogenesis of Knobloch syndrome, thus expanding the understanding of genes associated with syndromic retinal dystrophies." (PMID 41153400, 2025). "Seven cases of PAK2-associated Knobloch syndrome, including our case, were reviewed." (PMID 40262506, 2025). "There are two types of Knobloch syndrome: Type 1, caused by mutations in the COL18A1 gene, which disrupts collagen production, a key structural protein; and Type 2, linked to mutations in the PAK2 gene, which regulates cell growth and signaling." (PMID 40262506, 2025).
liver cancer (2 papers, 2021 to 2022). An epithelial or non-epithelial malignant neoplasm that arises from the liver. "PAK1 and PAK2 are overexpressed in breast and liver cancer, and promote the occurrence and development of tumors." (PMID 34307365, 2021).
liver fibrosis (2 papers, 2021 to 2023). "Our study demonstrated that HUC-MSCs significantly alleviate HSC activation and CCl4-induced liver fibrosis in a mouse model; overexpression of miR-455-3p by targeting PAK2 might be the underlying mechanism for the therapeutic effects of HUC-MSCs in hepatic fibrosis." (PMID 33708992, 2021). "In conclusion, our findings revealed that HUC-MSCs alleviated hepatic fibrosis through upregulating miR-455-3p by targeting PAK2." (PMID 33708992, 2021). "Taken together, our study suggests that HUC-MSCs inhibit the activation of HSCs and mouse CCl4-induced liver fibrosis by upregulation of miR-455-3p through targeting PAK2." (PMID 33708992, 2021). "Finally, our results demonstrated that HUC-MSC treatment ameliorated liver fibrosis by upregulating miR-455-3p through suppression of p21-activated kinase-2 (PAK2)." (PMID 33708992, 2021). "In vivo, we also found that HUC-MSCs could upregulate miR-455-3p and inhibit PAK2 in a mouse hepatic fibrosis model." (PMID 33708992, 2021).
microcephaly (2 papers, 2015 to 2020). A congenital or acquired developmental disorder in which the circumference of the head is smaller than normal for the person's age and sex. "Other genes within the combined network are involved in neuronal progenitor cell proliferation, a common mechanism underlying microcephaly (RAC1 and GNB1) and neuronal development (CEBPB, L1CAM, MAPT, PAK2, SPTBN1, and YWHAE)." (PMID 25781962, 2015).
multiple myeloma (2 papers, 2017 to 2022). "SurvExpress data revealed that levels of PAK2 are significantly elevated in high‐risk groups of patients suffering from Burkitt lymphoma (BL), multiple myeloma (MM), diffuse large B‐cell lymphoma (DLBCL), and mantle cell lymphoma (MCL)." (PMID 28707321, 2017).
Obesity (2 papers, 2015 to 2026). Accumulation of substantial excess body fat. "Lastly, our study identifies several differently regulated proteins whose role in obesity and adipose tissue is poorly known, such as ANXA8, DDX39B, STX7, SYNCRIP, SYNGR2, and PAK2." (PMID 41077621, 2026).
osteosarcoma (2 papers, 2015 to 2025). A usually aggressive malignant bone-forming mesenchymal neoplasm, predominantly affecting adolescents and young adults. "Depletion of Tiam1 or Pak2 in U2OS (human osteosarcoma) cells also led to increased intercentrosomal distance in prophase." (PMID 26078008, 2015).
pancreatic ductal adenocarcinoma (2 papers, 2018 to 2020). An infiltrating adenocarcinoma that arises from the epithelial cells of the pancreas. "PKM2 directly phosphorylates the p21-activated kinase 2 (PAK2) at four Ser residues and enhances PAK2 stability through PAK2 phosphorylation-induced HSP90 binding, facilitating the metastasis of pancreatic ductal adenocarcinoma." (PMID 33292198, 2020).
Purpura Fulminans (2 papers, 2023 to 2025). A severe, rapidly fatal reaction occurring most commonly in children following an infectious illness. "Bilateral retinal detachment, chylothorax, and purpura fulminans in a neonate with a PAK2 genetic variant is uncommon." (PMID 40262506, 2025).
retinoblastoma (2 papers, 2013 to 2019). A malignant tumor that originates in the nuclear layer of the retina. "PAK2 plays a role in apoptosis and activation of Rac, while HMGB2 is participating in chromatin regulation and retinoblastoma in cancer." (PMID 30988666, 2019). "We observed that PAK2 and MLCK were down-regulated in Tiam1 silenced retinoblastoma Y79 cells." (PMID 23950931, 2013).
Salmonella Infections (2 papers, 2013 to 2021). Infections with bacteria of the genus SALMONELLA. "Cushing syndrome, transcriptional misregulation in cancer, and TCONS_00000537 (PAK 2) were annotated in three pathways (e.g., salmonella infection, yersinia infection, and PI3K-Akt signaling pathway, respectively)." (PMID 34944311, 2021). "Furthermore, Salmonella infection has been shown to robustly activate PAK2." (PMID 24098123, 2013).
small cell lung carcinoma (2 papers, 2015 to 2020). Small cell lung cancer (SCLC) is a highly aggressive malignant neoplasm, accounting for 10-15% of lung cancer cases, characterized byrapid growth, and early metastasis. "For example, miR-216a-5p was shown to contribute to tumor regression by targeting PAK2 or Bcl-2 family proteins in breast and small cell lung cancers." (PMID 32792860, 2020). "Since PAK3 protein is expressed at very low levels in HeLa and CaSki cells, and migrates with PAK2, which can also be detected by the N-19 PAK3 antibody, PAK3 protein knockdown was examined in a PAK3 high expression small cell lung carcinoma cell, DMS-79." (PMID 25615606, 2015).
acute myeloid leukemia (1 paper, 2022). Acute myeloid leukemia (AML) is a group of neoplasms arising from precursor cells committed to the myeloid cell-line differentiation. "In addition, we found that the expression of PAKs in most tumors was distinctly higher than that in the corresponding normal tissues, while PAK1, PAK2 and PAK4 showed the most significant differences but only in Cholangiocarcinoma (CHOL) and Acute Myeloid Leukemia (LAML)." (PMID 36064705, 2022).
acute pancreatitis (1 paper, 2025). An acute inflammatory process that leads to necrosis of the pancreatic parenchyma. "For the stimulation of apoptosis in acute pancreatitis, the activation of caspases 3, 8 and 9 plays an essential role, and, in this recent study, the activation of these caspases required the activation of PAK2." (PMID 40001881, 2025). "Furthermore, the activation of reactive oxygen species [ROS] has been reported to play an important role in the pathobiology of acute pancreatitis in various disease models, and this was also found to be dependent on the activation of PAK2." (PMID 40001881, 2025). "The authors of this study propose that because of the multiple roles of PAK2 in the pathobiology of experimental acute pancreatitis, PAK2 could be an important therapeutic target for the treatment of acute pancreatitis." (PMID 40001881, 2025). "Furthermore, the activation of PAK2 was an important mediator of necrosis in this model of acute pancreatitis." (PMID 40001881, 2025). "The premature activation of the pancreatic digestive enzyme, trypsinogen to trypsin, in the pancreatic acinar cell is considered to be one of the main initiating events in acute pancreatitis; in this experimental model of acute pancreatitis, this required the CCK activation of PAK2." (PMID 40001881, 2025).
adult T-cell leukemia/lymphoma (1 paper, 2025). A peripheral (mature) T-cell neoplasm linked to the human T-cell leukemia virus type 1 (HTLV-1), adult T-cell leukemia/lymphoma is endemic in several regions of the world, in particular Japan, the Caribbean, and parts of Central Africa. "PAK2 amplification is frequently observed in Adult T-cell Leukemia/Lymphoma (ATLL) caused by T-cell lymphotropic virus, promoting CADM1-mediated interactions and enhancing the survival of ATLL cells." (PMID 40332759, 2025).
allergic asthma (1 paper, 2024). A asthma with a basis in a pathological type I hypersensitivity reaction. "The genes associated with mucin production (GAL3ST2), leukotriene synthesis (GPX4), Th2-mediated allergic asthma (PTBP1, ZFPM1, SBNO2, and EGFL7), and IgE mediated allergy (PAK2) were also represented in our polygenic prediction models of ICS response." (PMID 38540988, 2024).
anemia (1 paper, 2021). A reduction in the number of red blood cells, the amount of hemoglobin, and/or the volume of packed red blood cells. "Cell-specific genetic deletion of PAK2 in hematopoietic stem cells (HSCs) resulted in severe leukopenia and mild macro-cellular anemia via decreased expression of Jun-B and increased gene expression of c-Myc in a conditional PAK2 knockout mouse model." (PMID 33796531, 2021).
aneuploidy (1 paper, 2023). Chromosomal disorder consisting of the presence a chromosomal abnormality in which there is an addition or loss of chromosomes within a set. "If these attachment errors are not corrected prior to anaphase in normal oocyte maturation, they may cause chromosome-separation defects; and consistent with this concept, the frequency of aneuploidy was significantly increased in Pak2-depleted oocytes relative to controls." (PMID 36813765, 2023).
Arrhythmia (1 paper, 2025). Any cardiac rhythm other than the normal sinus rhythm. "The increased activation of Pak2 by JB2019A reduced arrhythmia and cardiac remodeling in both acute adrenergic and chronic TAC stress conditions." (PMID 40068092, 2025).
atrial fibrillation (1 paper, 2025). A disorder characterized by an electrocardiographic finding of a supraventricular arrhythmia characterized by the replacement of consistent P waves by rapid oscillations or fibrillatory waves that vary in size, shape and timing and are accompanied by an irregular ventricular response. "Pak2 was reduced and NOX4 increased in atrial appendage tissue from cardiopulmonary bypass patients with atrial fibrillation compared to patients with sinus rhythm." (PMID 40068092, 2025). "Similarly, cardiac tissue from AF patients, showed a Pak2 downregulation and NOX4 upregulation implicating these changes in human atrial fibrillation." (PMID 40068092, 2025).
benign meningioma (1 paper, 2015). A grade I, slowly growing meningioma. "Similar results were observed in an NF2-deficient benign meningioma cell line, Ben-Men1-LucB, hereafter referred to as Ben-Men, in which expression level diminished by 54% and 58% for Pak1 and Pak2, respectively." (PMID 25596744, 2015).
cerebral cavernous malformation (1 paper, 2016). A disorder characterized by malformations in the structure of the capillaries in the brain. "Src activity has been reported to inhibit the Rho/Rock pathway, a pathway also inhibited by Pak2/Pak4, Rasip1/Arhgap29, and the cerebral cavernous malformation (CCM) proteins, CCM1 and CCM2." (PMID 26812085, 2016).
cerebrovascular diseases (1 paper, 2024). "Theoretically, the inhibitors of PAK1 and PAK2 may also affect vascular function and related diseases; modulating PAK1 and PAK2 activity will be useful in treating dysfunctional vascular problems, such as hypertension, diabetic retinopathy, and cerebrovascular diseases." (PMID 39766303, 2024).